GLI1 (GLI family zinc finger 1)
Diseases named in the same sentence as GLI1 in open-access papers (continued):
Sharing a sentence is not in itself a finding about the gene and the disease.
tumor (continued). "Our work identifies Gli1 as a promising therapeutic target in ES and demonstrates that GANT61, through inhibition of Gli1 transcriptional activity, may be a promising therapeutic strategy hindering ES tumor progression, and specifically primary tumor growth." (PMID 33228057, 2020). "Moreover, GLI1 co-expressed and DEGs between tumor samples and normal tissues were both largely enriched in the PI3K–Akt pathway in STAD." (PMID 33365328, 2020). "Subsequently, decreases in tumor size may have contributed to reductions in GLI1 levels measured following treatment." (PMID 32973971, 2020). "Significant positive levels of GLI1 were present in 62% (37/60) of primary EAC tumor tissues." (PMID 32913560, 2020). "Aberrant GLI1 activation promotes tumor growth, migration, and angiogenesis." (PMID 32973971, 2020). "Large-scale datamining from gene expression datasets representing 23,500 patients and 37 types of neoplasms addressed the issue of whether GLI1/2 expression in tumors warrants therapeutic approaches targeting upstream HH signaling." (PMID 32879407, 2020). "The chemotherapy-altered factors in the tumour microenvironment that lead to the upregulation of GLI1 may be different." (PMID 32242101, 2020). "However, distinct tumor nests of approximately 50% of the tumors express GLI1, which is the major downstream target of HH signaling." (PMID 31867038, 2019). "As in mouse cells, I-BET151 significantly reduced GLI1 expression in human tumor cells." (PMID 31085420, 2019). "Indeed, it has been identified as a tumour suppressor that limits GLI1 oncogenic properties, and enforces SuFu tumour suppressor functions, thus keeping the Hh pathway off." (PMID 30699938, 2019). "The molecular pathway of PF development implicates that such neoplasms with GLI1 oncogenesis may be sensitive to Hedgehog pathway inhibitors, targeting either Patched, Smoothened, GLI1, or other Hedgehog pathway components." (PMID 31360694, 2019). "Although we have not found any reports devoted to this relationship in the context of BCC, studies based on different neoplasia showed that IL-6 may upregulate Shh and Gli-1 expression." (PMID 31342143, 2019). "Specifically, taking advantage from our previous work, we have designed an isoflavone with the aim to target simultaneously the Hh pathway at both upstream and downstream level, i.e., Smo and Gli1 respectively, and identify an innovative approach to limit tumor growth." (PMID 31601026, 2019). "It suggested that L-4 inhibited MB tumor growth by inhibiting Hh pathway and Gli1 and Ptch1 might be important pharmacodynamic markers." (PMID 30846937, 2019). "Human cSCC samples highly express EGFR, whereas GLI1 is only expressed in distinct tumor areas." (PMID 31867038, 2019). "GLI1 plays a significant role in tumor growth, differentiation, metastasis, and therapy resistance." (PMID 31783569, 2019). "The overproduction of GLI1 protein has been recognized in a wide range of neoplasms and occurs via activation of the Hedgehog signaling pathway, which plays important roles in gastrointestinal developments, diseases, and neoplasms." (PMID 31360694, 2019). "In a potential paracrine activation, Shh expression in the tumor cells can be associated with the increased interpretation of Ptch1 and Gli1 in the adjacent stromal cells, which was not evident in this series of experiments." (PMID 30769952, 2019). "Furthermore, the expression of PTCH1 and GLI1 was only visible in the tumor cell nucleus in cranial, spinal primary tumors and relapses." (PMID 30769952, 2019). "In addition, GLI1 is highly expressed in breast CSCs, and a study in an orthotopic xenografts model showed that low expression of GLI1 reduces tumor growth, self-renewal, motility, and viability of breast CSCs." (PMID 30423843, 2018). "Furthermore, it is believed that Gli1 expression is also responsible for chemoresistance in gliomas and that it’s overexpression is related to tumor recurrence after treatment." (PMID 29558958, 2018).
tumor (continued). "Consequently, it has been demonstrated that NQC reduces GLI1-dependent proliferation and tumor growth." (PMID 29695137, 2018). "Moreover, in models of primary cultures of MPM, Smo inhibition induced a significant decrease in tumor growth through Gli1 inhibition." (PMID 29581874, 2018). "They demonstrated that degradation of GLI1 is regulated by two independent destruction signals called degron DC and degron DN, and that amino acid changes in one or both degrons stabilize GLI1 protein and rapidly accelerates tumor formation in transgenic animals." (PMID 30158435, 2018). "However, abnormal expression of Gli-1 is highly correlated with tumor development, such as in the brain, muscle, and skin." (PMID 29867331, 2018). "Moreover, the expression levels of Shh, Smo and Gli1 were also notably increased in smoker tumor tissues." (PMID 29540668, 2018). "SRF has been shown to move into the nucleus in association with the transcriptional cofactor megakaryoblastic leukemia 1 (MLK1), where together they form a protein complex with GLI1 that enhances the transcription of HH pathway target genes and drug-resistant tumor growth." (PMID 30558232, 2018). "It explained the role Gli1 plays in the tumor growth and metastasis." (PMID 29321573, 2018). "The results suggested a possible role of mGluR4 in suppression of GBM growth, which may involve the inhibition of Gli-1 signaling in tumor cells." (PMID 29867331, 2018). "Furthermore, tumor growth inhibition correlated with Gli1 expression levels, which suggests that Gli1 is a perfect biomarker for the antitumor effects of SMO inhibitors in Ptch mutant ERMS." (PMID 30319965, 2018). "Such an effect was likely caused by the inability of the SuFuK321/457R mutant to suppress the tumour cell proliferation as suggested by increased expression of Ki67 and Gli1 observed in mice engrafted with the SuFuK321/457R mutant compared to mice engrafted with wild-type SuFu." (PMID 29515120, 2018). "In this regard, we hypothesize that mGluR4 is expressed in GBM cells; activity of mGluR4 may regulate the growth of the tumor cells; and Gli-1 transcript factor may be an intracellular target of mGluR4." (PMID 29867331, 2018). "Interestingly, the group did molecular analyses of the patient’s tumor specimens obtained before treatment which suggested activation of Shh pathway, as there was a high expression of Hh target genes including GLI1, PTCH1, PTCH2 and sFRP1." (PMID 29558958, 2018). "However, this can be misleading as GLI1 can be regulated independently of the HH pathway, and it can exhibit an increased copy number in tumour DNA which influences its expression level independently of the HH pathway." (PMID 30068568, 2018). "To confirm whether NUSAP1 promotes tumor aggressiveness by activating the HH pathway, we induced knockdown of the expression of GLI1 by small interfering RNA in NUSAP1-transduced SW1008 cells." (PMID 28899410, 2017). "We next tested whether SHH could be the ligand responsible for Gli1 expression near tumor cells by examining ShhnlacZ expression in PB-MYC and TRAMP tumors." (PMID 27935821, 2017). "Importantly, in Gli1-deficient SHH MB cells, where p21 is upregulated and tumor cell growth is inhibited compared to controls, mocetinostat is unable to cause any further increase of p21 or inhibition of cell growth." (PMID 28276480, 2017). "The exclusive expression of tGli1 in tumor tissues and its unique role in tumorigenesis make it a potential target in anticancer therapies but by far no small molecular inhibitor has been developed against this shortened Gli1 subtype." (PMID 29249966, 2017).
tumor (continued). "Eight pairs of fresh samples were randomly collected and assessed using Western blotting, which showed that the expression levels of both FoxM1and Gli1 protein were significantly higher in the CRC tumor tissues than in their matched adjacent normal colorectal tissues." (PMID 28148279, 2017). "On account that Gli1 acts as terminal foci for numerous other oncogenic pathways, whence omeprazole may display anti-tumor effects via its inhibitory effects on Hh/Gli1 signaling." (PMID 29375376, 2017). "Indeed, Gli1 ablation reduces the proliferation of these tumor cells, and abrogates the response to MGCD0103." (PMID 28276480, 2017). "Our primary endpoint was pharmacodynamics, determining whether the Hedgehog pathway is measurable in untreated localized disease and whether Sonidegib treatment penetrates tumor tissue and downregulates Hedgehog signaling as assayed by GLI1 expression." (PMID 29262631, 2017). "GLI1 expression was notably increased (p < 0.043) in tumor tissues relative to normal tissues." (PMID 28112165, 2017). "In keeping with these data, MGCD0103 treatment did not induce any further inhibition of tumor growth or upregulation of p21 in Gli1-deficient cells, indicating that the antitumor properties of this drug are dependent on Gli1 in these cells." (PMID 28276480, 2017). "However, the tumor growth was significantly blocked by cyclopamine possibly due to an activated HH/Gli1 signaling in these cancer cells." (PMID 29225516, 2017). "Also, Activated Gli1 was found in 85% of CD44+ tumor cells suggesting that Gli1 was a potential molecular target." (PMID 29029546, 2017). "In this study, we observe the same variation of GLI1 levels and show that this variability could be correlated with the aggressiveness of the BCC tumor, where lower GLI1 expression levels correspond to more aggressive BCC subtypes." (PMID 29137400, 2017). "This approach is clearly preferable to simply comparing the mean or median GLI1 expression in post-treatment tumor samples in Sonidegib-treated patients versus controls, which would not account for dynamic changes in the biomarkers of interest induced by Sonidegib treatment." (PMID 29262631, 2017). "However, a major strength of this study was our ability to assess intra-patient changes in GLI1 levels by interrogating pre-treatment and post-treatment tumor tissue in each individual patient." (PMID 29262631, 2017). "This combination also down-regulated MMP-2, MMP-9, Shh and Gli-1 in tumor xenografts." (PMID 29157266, 2017). "Nuclear staining of Gli1 is a reliable indicator of HH pathway activity in tumor cells." (PMID 29225516, 2017). "GLI1 expression was the same in normal prostate and all types of tumor samples, which could indicate an actual increase in stromal expression as the proportion of stromal cells is reduced." (PMID 27935821, 2017). "Additionally, the Hedgehog (Hh) signaling pathway regulates tumor invasion and metastasis, with its mediators Shh and Gli-1 over-expressed in OSCC." (PMID 29157266, 2017). "We found that GLI1 knockdown significantly reduced the size of tumor spheres." (PMID 28404967, 2017). "It thus appears that high GLI1 expression increases the tumor sphere forming efficiency." (PMID 28404967, 2017). "Gal-1 may have a variety of roles in tumor metastasis, and our research clearly showed that Gli1 is involved in the promotion of EMT-induced metastasis by Gal-1." (PMID 27836001, 2016). "This indicated that Gli-1 probably presented a vital function in tumorigenesis and tumor invasion." (PMID 27634907, 2016). "Therefore, when cyclopamine blocks SHH signaling to decrease Gli-1 mRNA expression, a corresponding decrease in Bcl-2 mRNA can occur, which can promote apoptosis of tumor cells." (PMID 26716648, 2016). "Additionally, the in vivo tumor growth rate of GLI1+shNANOG cells was significantly lower than control cells." (PMID 26189795, 2016).
tumor (continued). "Thus, inhibition of GLI1 in tumor cells sensitized them to chemotherapeutic agents that target DNA Topoisomerase I." (PMID 26988232, 2016). "This could be of particular relevance in tumours that express aberrant levels of Gli1 or that are otherwise activated downstream of Patched proteins and are thus resistant to the SMO inhibitor Vismodegib." (PMID 27621083, 2016). "In order to investigate whether the growth of tumor spheroids is dependent on ciliary SmoM2-induced Hh pathway activation, we analyzed Smo and Gprasp2 translocation to the PC and Gli1 protein expression as an indicator for Hh pathway activation." (PMID 26931153, 2016). "Immunohistochemistry (IHC) of β-catenin in tumours from Gli1lacZ/+ mice revealed its nuclear translocation in areas of low stromal Gli1 expression, substantiating a model in which the stromal downstream Hh signal is diminished in areas of high epithelial Wnt activity." (PMID 27492255, 2016). "Given the facts that tGLI1 is expressed in a tumor-specific fashion and behaves as a more potent transcription regulator compared to GLI1, an important task is warranted to target tGLI1-driven malignancies directly or indirectly by targeting its upstream regulators and downstream targets." (PMID 26891329, 2016). "Moreover, GANT61, a GLI1/2 inhibitor, repressed endogenous survivin protein and mRNA expression in most cells across a large panel of tumor cell lines." (PMID 26775700, 2016). "The IHC positive staining of CD44, Shh, and Gli1 proteins was correlated with larger tumour size, worse gross type and histological type, and advanced TNM stage, which also predicted shorter overall survival (OS) and disease-free survival (DFS) after radical resection." (PMID 26839535, 2016). "Since Set7 can augment Shh activation by increasing Gli3 stability and its DNA binding ability on the promoter regions of Gli1, we then determined whether this Set7-Gli3-Gli1 axis plays a role in tumor development." (PMID 27146893, 2016). "ChIP analysis revealed that GLI1 binds to the DNMT1 promoter suggesting that GLI1 may regulate tumor-related genes through DNMT1 expression." (PMID 26633513, 2015). "EMT is a process that exerts influence on many molecular, such as TGF-β, E-cadherin, N-cadherin Vimentin, ZEB-1, SMAD-2, SMAD-3, SMAD-7, GLI1 and GLI2; these molecules are closely associated with typical phenotype changes of EMT in tumor cell growth and metastasis." (PMID 25895132, 2015). "Herein the stabilization of β-catenin at an early time point of the disease might have beneficial effects by directly targeting Gli1 and by supporting the chemotherapeutic treatment of the tumor cells." (PMID 25645196, 2015). "It will be interesting to note whether GLI1 alone is enough to induce tumor recurrence or if it works in combination with other oncogenic signals." (PMID 26633513, 2015). "Blocking GLI1 in these stem cells reduced tumor initiation and stem cell renewal." (PMID 26633513, 2015). "Furthermore, 3D reconstruction of confocal Z-stacks revealed the localization of a small fraction of β-catenin-Gli1 within the nucleus, whereas most of the complex localized to the cytoplasm of Ptch+/- MB tumor cells." (PMID 25645196, 2015). "Since the role of GLI1 varied within the different stages of tumor progression like hyperplasia, dysplasia, malignant and invasive tumor, the importance of oncogenes and their association with GLI1 at various stages of tumor progression has to be thoroughly analyzed." (PMID 26633513, 2015). "Inappropriate Hh signaling has been ascribed to either ligand-dependent, i.e. autocrine and/or paracrine signaling, or ligand independent tumor cell intrinsic pathway activation due to loss-of-function mutations in PTCH or SUFU and gain-of-function mutations in SHH, SMO or GLI1/2." (PMID 26053182, 2015). "It has been suggested that miR-202-3p is an inhibitor of proliferation and may function as a tumor suppressor by targeting Gli1 which mediates Myf5 expression during somitogenesis." (PMID 25630602, 2015).
tumor (continued). "Analysis of GLI1 status prior to treatment may allow development of tailored treatments to minimize incidence of tumor recurrence." (PMID 26633513, 2015). "Inhibition of GLI1 by siRNAs or GANT61 showed increased DNA damage, activation of ataxia telangiectasia-mutated protein kinase (ATM)-checkpoint kinase 2 (CHK2) and cell cycle arrest at G1–S and in early S-phase in many tumor cells that aberrantly express GLI1." (PMID 26633513, 2015). "Recent studies from our lab and other independent studies demonstrate that aberrantly expressed GLI1 influences the integrity of several DNA damage response and repair signals, and if altered, these networks can contribute to GI and impact tumor response to chemo- and radiation therapies." (PMID 26633513, 2015). "Compared with those from other groups, the expression of TGF-β1, Vimentin, ZEB-1, N-cadherin, Gli1/2, and P-Smad2/3 was significantly decreased in the tumor areas from the mice vaccinated with B16F10/GPI-IL-21 combined with the B16F10/shTGF-β1 challenge and the administration of miR200c agomir." (PMID 25895132, 2015). "Also, it has been described a positive correlation between GLI1 expression and tumor grade and/or lymph node status, pointing to a role of GLI1 in metastasis." (PMID 26258070, 2015). "Flow cytometry analysis further confirmed that Gli1 could promote tumor growth by inducing cell cycle arrest at the G0/G1 phase and consequently decrease apoptosis." (PMID 26317501, 2015). "For example, malignant prostate tissue evaluated retrospectively from radical prostatectomy specimens demonstrated increased levels of GLI1 protein (using immunohistochemical staining) compared to benign prostatic epithelium; elevated GLI1 levels were also correlated with increasing tumor grade." (PMID 26426053, 2015). "The CK2β staining was compared with CK2α and Gli1 expression in the same tumor samples (n = 61)." (PMID 25422081, 2014). "In addition, we analyzed the correlation between Gli1 expression and tumor pathological characteristics and patient prognosis." (PMID 25017332, 2014). "Inhibition of Gli1 induces DNA damage, cell cycle arrest, cell apoptosis and tumor metastasis." (PMID 25373737, 2014). "Multivariate analysis revealed higher GLI1 mRNA expression as an independent factor for unfavorable patient survival (P = 0.0030, hazard ratio = 3.1, 95% confidence interval = 1.5-6.2), as well as tumor differentiation and stage." (PMID 25103784, 2014). "In fact, recent studies investigating GLI1 expression in PDAC have revealed GLI1 may switch from a tumor promoting to a tumor protective molecule in the later stages of PDAC." (PMID 25352983, 2014). "In contrast to the current paradigm for GLI1 expression and tumor progression, one study found GLI1 expression may actually decrease cell motility in advanced PDAC (Joostet al., 2012)." (PMID 25352983, 2014). "In an analysis of a panel of tumor cell lines, the most abundant isoform was the 130-kDa protein and that the relative abundance of three different GLI1 isoforms was: GLI1-130kDa > GLI1-100kDa > GLI1 full length-160-kDa." (PMID 24366538, 2014). "Inhibition of nuclear Gli1 accumulation may explain for the suppression of the tumor-suppressive function of Gli1." (PMID 23900341, 2013). "However, prolonged (21 days) IPI-926 treatment led to significant decreases in both stromal and tumor Gli1 expression." (PMID 23303278, 2013). "Furthermore, Chaudary and colleagues correlated the gene expression of different Hh components (SHH, IHH, PTCH1, PTCH2, GLI1) with clinicopathological data (tumor hypoxia, local recurrence and DFS) from cervical adenocarcinoma samples after CRT." (PMID 23880852, 2013). "In addition, the presence of this alternative signalling pathway regulating GLI1 supports the existence of different tumour initiating cell types." (PMID 23505092, 2013).